CLDN1 (claudin 1)
Diseases named in the same sentence as CLDN1 in open-access papers (continued):
Sharing a sentence is not in itself a finding about the gene and the disease.
breast tumors (8 papers, 2005 to 2022). "A number of CLDN1 transcript variants were identified in these breast tumors." (PMID 27649506, 2016). "The same group found a similar loss of CLDN1 expression in five primary breast tumours." (PMID 15743508, 2005). "Although the similar CLDN3 and CLDN4 TJ proteins are highly expressed in breast neoplasia, we hypothesize that mechanisms other than alteration in TJs are involved in the loss of CLDN1 expression in breast tumours." (PMID 15743508, 2005). "Our results also showed membranous staining as well as cytoplasmic staining for claudin 1 in the breast tumors analyzed in the TMA." (PMID 23721519, 2013). "Claudin-1-transduced MDA-MB 361 breast tumor cell spheroids induced significant apoptosis." (PMID 35432533, 2022). "Claudin-1-transduced 3D in breast tumor spheroid culture displayed plasma membrane homing and reduced paracellular flux, which further supports this hypothesis." (PMID 35432533, 2022). "A number of CLDN1 SNPs were also identified in the breast tumor specimens." (PMID 27649506, 2016). "Clinico-pathological characteristics and claudin 1 protein levels in human breast tumors." (PMID 27649506, 2016). "Similarly, although the tight junction protein claudin 1(CLDN1) is often decreased in breast tumours, high expression has beendescribed in ER− tumours." (PMID 21633508, 2011). "The contradictory results from studies which addressed CLDNs expression concerning molecular subtypes, present findings could add an insight focusing on the association of CLDN-1-CLDN-4 and ROCK-CLDN-2 connected to breast tumors characterized by hormone receptor-positive." (PMID 33407452, 2021). "Results from this analysis revealed that claudin 1 protein levels in the 12 breast tumors ranged from not detectable or low (5/12 tumors) to very high (4/12 tumors)." (PMID 27649506, 2016).
Crohn disease (8 papers, 2019 to 2025). A gastrointestinal disorder characterized by chronic inflammation involving all layers of the intestinal wall, noncaseating granulomas affecting the intestinal wall and regional lymph nodes, and transmural fibrosis. "In Crohn’s disease, upregulation of claudin-1 and claudin-2 and decreased expression of intestinal epithelial isoforms claudin-3, -5, -8, and -12 were reported." (PMID 39334888, 2024). "Another example is herb-partitioned moxibustion, which can promote occludin, claudin-1, and ZO-1 expression, and recover the increased epithelial permeability in Crohn’s disease model rats." (PMID 30609730, 2019).
liver disease (8 papers, 2015 to 2024). "These genes encode for omentin (intelectin 1), claudin 1, polycystic kidney and hepatic disease 1 (autosomal recessive)-like 1, and annexin A8." (PMID 26636677, 2015). "Decreased expression of occludin and claudin-1 in the duodenal mucosa have also been reported in cirrhosis and their expression levels correlated with LPS concentrations, severity of liver disease and portal hypertension (esophageal varices)." (PMID 34513903, 2021). "For example, claudin-1 has been shown to be upregulated in advanced liver disease and HCC, and differential claudin-4 expression facilitates distinguishing between these two forms of cancer at the molecular level." (PMID 34338154, 2021). "The TJ proteins CLDN1 and OCLN on the basolateral membrane of hepatocytes serve as entry factors for HCV—a major cause of liver disease and cancer worldwide." (PMID 32012812, 2020). "Besides the secretion of bile and gastric juice decrease, liver cirrhosis-related portal hypertension can decrease the expression of occludin and claudin-1, both of which participate in the integrity of the mucosal." (PMID 38287258, 2024). "For example, claudin-1 has been shown to be up-regulated in advanced liver disease and HCC." (PMID 34338154, 2021). "A missense mutation in the first PDZ domain of ZO2, that binds to CLDN1 in TJs has further been described in patients with familial hypercholanemia, characterized by pruritus and fat malabsorption but without progressive liver disease." (PMID 32012812, 2020).
Salmonella Infections (8 papers, 2022 to 2024). Infections with bacteria of the genus SALMONELLA. "In the current experiment, dietary AC alleviated the adverse effects of chickens caused by Salmonella infection by up-regulating expression of ZO-1, claudin-1, occludin, and MUC2." (PMID 36670458, 2023). "Previous studies showed that Salmonella infection induced intestinal barrier injury by suppressing gene expression of tight junction proteins (ZO-1, claudin-1 and occludin) and MUC2." (PMID 36670458, 2023). "The down-regulation of ZO-1 and claudin-1 due to Salmonella infection was eliminated in the P+S group." (PMID 36032095, 2022). "In comparison with the C group, Salmonella infection (group S) significantly (P <0.05) decreased the mRNA levels of ZO-1 and claudin-1." (PMID 36032095, 2022). "B. animalis BB12 treatment increased claudin-1 protein mRNA expression in the ileum of germfree piglets post Salmonella infection." (PMID 36300953, 2022). "By analogy, Salmonella infection also reduced the expression of the OCLN and CLDN1 genes in the ileum and jejunum of broiler chickens and reduced the intestinal barrier function." (PMID 39682509, 2024).
viral infection (8 papers, 2012 to 2024). "Because disruption of the blood-tissue barrier during viral infection is mostly associated with the degradation or redistribution of TJPs, we assessed the staining of key TJPs, such as ZO-1, claudin-1, and occludin, by immunofluorescence analysis." (PMID 32302362, 2020). "Having ruled out the possibility that WNV infection affects the transcription and/or degradation of tight junction protein-encoding mRNAs, we next focused on determining how virus infection induces degradation of claudin-1 and JAM-1 proteins." (PMID 22655077, 2012). "IAV virus subtype H3N2 promotes viral infection by downregulating the expression of ZO-1, CLDN1 and OCLN when infecting ferret nasal epithelial cells." (PMID 36297257, 2022). "Other viruses that cause diarrhea, such as rotavirus, can infect intestinal epithelial cells and the distribution of tight junction proteins Claudin-1 and Occludin, thereby promoting viral infections." (PMID 33804466, 2021). "For example, overexpression of IFI6-16 inhibited genome replication and gene expression of HBV (hepatitis B virus) in HepG2 cells, and researchers also found that IFI6-16 could inhibit HCV (hepatitis C virus) infection by impairing EGFR mediated CD81 co-localization with claudin-1." (PMID 35632802, 2022). "However, we cannot rule out the possibility that viral infection causes misrouting of nascent claudin-1 and/or JAM-1 to lysosomes." (PMID 22655077, 2012). "In addition, both viral infection and perturbed gut microbiota have the potential to disturb the normal function of the gut barrier and lead to impaired intestinal permeability and the degradation of tight junction proteins, such as occludin, junctional adhesion molecule-A, and claudin-1." (PMID 38675974, 2024). "These drugs mainly inhibit the viral infection by inhibiting the interaction between CD81 and CLDN1." (PMID 36297257, 2022). "The changes in gene expression of ZO-1, Occludin, and Claudin-1 in this study suggest the destruction of ileal TJs after XMX infection, which can be observed in other reports about viral infection." (PMID 35891451, 2022).
C. perfringens infection (7 papers, 2018 to 2025). "In the present study, C. perfringens infection decreased the mRNA expression levels of Claudin-1 and Occludin genes in the ileum." (PMID 37138630, 2023). "C. perfringens infection significantly downregulated the mRNA expression of occludin and claudin-1 in the small intestine, as reported in previous studies." (PMID 34712727, 2021). "Similar with the result of MUC2 expression, the present study showed that C. perfringens infection significantly up-regulated the relative expression levels of ZO-1 and CLDN1, which was contrary to results from previous studies." (PMID 33679724, 2020). "Notably, C. perfringens infection significantly reduced (p < 0.05) the expression of Claudin-1 and Occludin genes, while the 40 and 120 mg Zn groups alleviated the decrease in Claudin-1 expression." (PMID 40559850, 2025). "In addition, C. perfringens infection suppressed the expression levels of claudin-1 and ZO-1, which were effectively alleviated by L. plantarum Lac16 preincubation." (PMID 34830269, 2021). "C. perfringens infection reduced the expressions of CLDN1 and TJP1, whereas the CF extract with or without butyrate tended to reverse the trend and enhanced both gene expressions." (PMID 35139922, 2022). "The relative mRNA levels of CLDN1 and ZO-1 expression in the jejunum were not significantly affected by C. perfringens infection or L. acidophilus treatment (P > 0.05)." (PMID 29599973, 2018).
colon adenocarcinoma (7 papers, 2013 to 2025). "In summary, CLDN-1 is expressed in all preneoplastic lesions of colonic adenocarcinoma, including SSA/P, MVHP, APC mutations, adenomatous polyps, and inflammatory bowel disease." (PMID 37627123, 2023). "In 2012, Bezdekova and co-workers reported strong claudin-1 expression in adenomas and adenocarcinomas of the colon." (PMID 37627123, 2023). "In colon adenocarcinoma, VPS9D1-AS1 can upregulate CLDN1 by sponging miR-1301-3p, thus facilitating colon adenocarcinoma cell growth suppressing apoptosis." (PMID 36105232, 2022).
E. coli infection (7 papers, 2018 to 2025). "Three pathways Cell adhesion molecules, Pathogenic Escherichia coli infection and Leukocyte transendothelial migration were associated with CLDN1." (PMID 36991484, 2023). "The results showed that E. coli infection impaired intestinal barrier function, manifested by downregulation of Occludin and Claudin-1 mRNA expression in the jejunum." (PMID 41463799, 2025). "E. coli infection significantly decreased ZO-1, claudin-1 and occludin mRNA expression, as compared with their expression levels in the NC mice." (PMID 29402269, 2018). "A previous study in Holstein male calves found that Escherichia coli infection could down-regulate the gene expression of tight junction proteins, including claudin-1, occludin and and ZO-1." (PMID 39901713, 2025).
esophageal squamous cell carcinoma (7 papers, 2016 to 2022). Esophageal squamous cell carcinoma (ESCC) is a type of esophageal carcinoma (EC) that can affect any part of the esophagus, but is usually located in the upper or middle third. "Given that CLDN1 is mostly found in the nucleus of esophageal squamous cell carcinoma (ESCC) and has been shown to be abnormally elevated, CLDN1 promotes ESCC growth and metastasis by upregulating the expression of ULK1 via the AMPK/STAT1 signaling pathway." (PMID 36620607, 2022). "In contrast, an inverse relationship between phosphorylation of Akt and CLDN1 expression is reported in esophageal SCC cells." (PMID 31551535, 2019). "Nm23H1 mediates tumor invasion in esophageal squamous cell carcinoma by regulation of CLDN1 through the AKT signalling." (PMID 28055967, 2017). "Previously, low expression of metastasis suppressor Nm23H1 and tight junction (TJ) protein claudin-1 (CLDN1) have been known to correlate with poor prognosis in esophageal squamous cell carcinoma (ESCC)." (PMID 27376780, 2016).
hepatitis C virus infection (7 papers, 2009 to 2021). A viral infection caused by the hepatitis C virus. "It has been reported that polymorphisms in CLDN1 are associated with the risk of cancer, small vessel vascular dementia, leukoaraiosis, and hepatitis C virus infection." (PMID 30910845, 2019). "Others, found in the CLDN1 promoter region, have been shown to confer susceptibility to hepatitis C virus infection." (PMID 27649506, 2016). "In addition, hepatitis C recurrence after liver transplantation is associated with an increase of claudin-1 and occludin expression at the hepatocyte cell membrane." (PMID 26731658, 2016). "In this paper, we describe a complete pipeline for screening of phage display libraries of human scFvs against native Claudin-1, a tight-junction protein involved in hepatitis C virus infection, expressed on the cell surface of human hepatocytes." (PMID 26649313, 2015). "On the other hand, it has been reported that in hepatitis C virus infection, multiple receptor molecules, including SR-B1, low-density lipoprotein receptor, CD81, claudin-1, occluding, epidermal growth factor receptor, and EphA2 are involved in its process." (PMID 34372540, 2021).
Cirrhosis (6 papers, 2019 to 2024). A chronic disorder of the liver in which liver tissue becomes scarred and is partially replaced by regenerative nodules and fibrotic tissue resulting in loss of liver function. "Cirrhosis induced a significant downregulation of tight-junction proteins Claudin 1 and ZO-1 and the upregulation of the gut vascular marker PV1 compared to control animals." (PMID 39656486, 2024). "The authors reported that in samples where hepatocellular carcinoma developed in a background of cirrhosis, even higher claudin-1 levels were present, whereas claudin-7 showed decreased levels in those same samples." (PMID 37627123, 2023). "We have previously reported that the expression of claudin 1 and occludin is decreased in the intestinal epithelial cells of cirrhotic patients, especially in decompensated cirrhosis, indicating gut barrier impairment." (PMID 35308545, 2022). "OCA treatment in cirrhosis also increases expression of claudin-1." (PMID 34831429, 2021). "In bile duct ligation (BDL), a model of cholestasis and cirrhosis, barrier integrity is restored in ileum of rats by treatment with OCA via increased expression of TJPs claudin-1 and occludin." (PMID 34831429, 2021). "In addition to claudin-4 and -7, claudin-1 also was significantly elevated in cirrhosis compared to non-cirrhotic liver." (PMID 37627123, 2023). "Similarly, the transcriptional levels of peripheral Cldn1 and TGF-β were significantly higher in patients with HCC and non-malignant cirrhosis than in patients without cirrhosis (P = 0.0185–<0.0001 and 0.0089–<0.0001, respectively)." (PMID 39548562, 2024).
colorectal adenocarcinoma (6 papers, 2013 to 2025). The most common type of colorectal carcinoma. "In vitro experiments showed that rTsNas14 can down-regulate the expression of occludin and claudin-1 proteins of human colorectal adenocarcinoma (Caco-2) cells and improve the permeability of an intestinal barrier model." (PMID 40839561, 2025). "In accordance, PCR experiments revealed a high level of expression of claudin-1, -3, and -4 in tissue samples from patients with colorectal adenocarcinomas." (PMID 34638619, 2021). "In recent years, the complex function of claudin-1 in tumors was unraveled by analyzing the expression of claudin-1 in colorectal adenocarcinoma and normal mucosa." (PMID 32855635, 2020). "In this way, it has been demonstrated that the overexpression of miR-21 downregulated both Claudin-1 and E-cadherin expression promoting the epithelial-to-mesenchymal transition (EMT) and the invasiveness of colorectal adenocarcinoma cells." (PMID 38892168, 2024). "Initially, we examined changes in the expression levels of claudin-1 and claudin-3 after EGF treatment in two colorectal adenocarcinoma cell lines, Caco-2 and HT-29, which differ in differentiation status and metastatic potential." (PMID 24069372, 2013).
glioma (6 papers, 2016 to 2026). A benign or malignant brain and spinal cord tumor that arises from glial cells (astrocytes, oligodendrocytes, ependymal cells). "Likewise, Ishihara and colleagues analyzed 24 cases of both low- and high-grade gliomas and reported a loss of CLDN1 expression in high-grade tumors." (PMID 41399659, 2026). "Reduced CLDN1 expression was observed in glioma cell lines derived from high-grade (grade 3 and 4) tumors, compared to low-grade pilocytic astrocytomas (grade 1), diffuse astrocytomas (grade 2), and non-neoplastic control tissues." (PMID 41399659, 2026). "The main conclusion of the present study is that reduced expression CLDN1 and CLDN5 are linked to the advancement of malignant gliomas, with this effect becoming more evident as the grade of glioma increases." (PMID 41399659, 2026). "The expression of β-catenin gradually increased in higher glioma tumor grades, while the expression of TJ proteins CLDN1 and CLDN5 were both decreased." (PMID 38147228, 2024). "Downregulation of claudin-1, claudin-5, and occludin has been repeatedly reported in gliomas." (PMID 35910247, 2022). "Moreover, the expression levels of claudin-1 and claudin-5 decrease with increasing severity of the glioma, according to World Health Organization (WHO) grading." (PMID 35910247, 2022). "Here, we found that ING5 up-regulated the Claudin 1 expression, but down-regulated the expression of N-cadherin, Slug, Snail, Twist, Zeb1 and Zeb2, indicating that ING5 suppressed the EMT in glioma." (PMID 28915612, 2017). "Moreover, overexpression of CLDN3 support progression and metastasis of these malignancies, while reduced expression of CLDN1 and CLDN5 is observed in advanced gliomas." (PMID 41399659, 2026).
Hyperglycemia (6 papers, 2021 to 2025). An increased concentration of glucose in the blood. "We found that claudin-1 expression was reduced in the left ventricular wall, right ventricular wall, and interventricular septum of hearts exposed to hyperglycemia, which may underlie the observed morphological abnormalities." (PMID 36983924, 2023). "Regarding intestinal barrier function, tight junction proteins zona occludens 1 (ZO-1), OCLN, and claudin 1 (CLDN1) are crucial for maintaining barrier integrity, with hyperglycemia altering their expression." (PMID 41359105, 2025). "To analyze changes in occluding junctions under hyperglycemia, we first measured the expression levels of ZO-1 and claudin-1 by immunostaining." (PMID 36983924, 2023). "In vitro, using human colon stem cells, we show that transient hyperglycemia induces persistent suppression of CLDN1 and ZO1 through epigenetic modifications, and that SOD2 expression reverses, while short‐hairpin (sh)SOD2 expression mimics, this effect." (PMID 35220596, 2022). "We also investigated the effects of hyperglycemia on gene expression of tight junction proteins ZO-1 (TJP1), Claudin 1 (CLDN1), and Occludin (OCLN)." (PMID 38110453, 2023). "We evaluated the potential effect of transient hyperglycemia on the expression of tight junction proteins ZO1, CLDN1, and OCLN." (PMID 35220596, 2022). "The results showed that 4‐day hyperglycemia plus 4‐day normoglycemia (HG(4d) + LG(4d)/CTL) treatment significantly suppressed mRNA levels of ZO1 and CLDN1, compared with the LG plus 4‐day normoglycemia (LG(4d) + LG(4d)/CTL) treatment." (PMID 35220596, 2022). "In our study here, we found that transient hyperglycemia induced persistent suppression of tight junction proteins, including ZO1 and CLDN1, in human epithelial cells due to epigenetic changes." (PMID 35220596, 2022). "Furthermore, we evaluated the possible effect of hyperglycemia and SOD2 expression on H4 methylation and histone acetylation on the CLDN1 (online only) and ZO1 (online only) promoters; neither showed any changes." (PMID 35220596, 2022).